ZNF285 (zinc finger protein 285)
Description:
May be involved in transcriptional regulation.
Synonyms: ZNF285A
Tractability: PROTAC: ubiquitination databases record sites on it.
Gene: Protein-coding gene on chromosome 19 (44,382,298 to 44,401,608, reverse strand). Ensembl gene ENSG00000267508.
Subcellular location: Nucleus
Pathways (Reactome):
Gene expression (Transcription): Generic Transcription Pathway
Gene Ontology:
Molecular function: protein binding; DNA-binding transcription factor activity; DNA binding
Biological process: regulation of DNA-templated transcription
Cellular component: nucleus
Genetic constraint (gnomAD): Loss-of-function variants: 5 observed, 7.5 expected, observed/expected ratio (o/e) 0.67, 90% interval 0.35 to 1.39. That is too few expected variants to judge how well the gene tolerates losing a copy. Missense variants: 695 observed, 729.75 expected, observed/expected ratio (o/e) 0.95, 90% interval 0.89 to 1.01. Synonymous variants: 240 observed, 252.42 expected, observed/expected ratio (o/e) 0.95, 90% interval 0.86 to 1.06.
Homologues: Orthologues: chimpanzee ZNF285 (96% identical), dog ZNF285 (77% identical). Paralogues in human: ZNF233 (44% identical), ZNF214 (41% identical), ZKSCAN7 (36% identical), ZNF852 (36% identical), ZNF287 (36% identical), ZNF17 (35% identical), ZNF155 (35% identical), ZNF530 (35% identical), ZNF527 (34% identical), ZNF230 (34% identical), ZNF34 (33% identical), ZNF222 (33% identical), and 38 more.